LCN2 (lipocalin 2)
Diseases named in the same sentence as LCN2 in open-access papers (continued):
Sharing a sentence is not in itself a finding about the gene and the disease.
psoriasis (77 papers, 2010 to 2026). An autoimmune condition characterized by red, well-delineated plaques with silvery scales that are usually on the extensor surfaces and scalp. "Using the IMQ-induced psoriasis model, we found that Aim2 deficiency reduces mRNA expression of the KC markers Lcn2, Krt14, and S100a9." (PMID 39352743, 2024). "A recent study underlies the role of lipocalin-2 in the pathogenesis of psoriasis and its link with disease severity." (PMID 38399624, 2024). "In order to further explore the relationship between hub genes and the mainstream pathogenic mechanism of psoriasis, we analyzed the relationship between these genes and LCN2/IL17A." (PMID 33613635, 2021). "Lcn-2 is upregulated in psoriatic skin both in human and in mice models, and it appears to have a pathogenic role in psoriasis." (PMID 33238518, 2020). "Epidermal dysfunction and keratinocyte injury were suggested to be at least some of the causes inducing keratinocytes to secrete Lcn-2 in psoriasis." (PMID 33238518, 2020). "This meta-analysis showed significant association between serum lipocalin-2 concentrations and psoriasis/PsA in overall population (SMD: 0.757, 95%CI = 0.588‐0.926, and PH = 0.114; PH is the P value for the heterogeneity test)." (PMID 31467617, 2019). "Our meta-analysis included eight case-control studies which were about the association between serum lipocalin-2 levels and psoriasis/PsA." (PMID 31467617, 2019). "The meta-analysis indicated the significant association between serum lipocalin-2 concentrations and psoriasis/PsA susceptibility in the overall population (SMD: 0.757, 95%CI = 0.588‐0.926, PH = 0.114)." (PMID 31467617, 2019). "The strength of association between serum lipocalin-2 concentrations and psoriasis/PsA was assessed by pooled standard mean difference (SMD) with its 95% confidence intervals (CIs)." (PMID 31467617, 2019). "Serum LCN2 concentrations were measured by enzyme-linked immunosorbent assays (ELISA) in patients with psoriasis and AD and in healthy controls." (PMID 30805373, 2019). "A systematic search of studies on the association of serum lipocalin-2 concentrations with psoriasis/PsA was conducted in PubMed, Web of Science, Elsevier ScienceDirect, and Cochrane Library." (PMID 31467617, 2019). "The purpose of this study was to explore the association of serum lipocalin-2 concentrations with psoriasis and psoriatic arthritis (PsA)." (PMID 31467617, 2019). "Moreover, high serum levels of LCN2 were found to be associated with the degree of itch in patients suffering from psoriasis and decreased after biologic treatment in psoriatic patients complaining of itch." (PMID 39063581, 2024). "They introduced Card14ΔE138K/A mutations in mice with psoriasis and found an up-regulation of pro-inflammatory cytokines, IL-23, IL-19, IL-22 and IL-17; chemokines Cxcl1, Ccl20, and Cxcl2; and antimicrobial peptides, Lcn2 and Defb4." (PMID 36012602, 2022). "In addition, recent studies have shown that human LCN2 is expressed in the skin and is associated with wound healing and certain skin diseases, such as psoriasis." (PMID 31091692, 2019). "However, more large-scale studies are warranted to explore the association between serum lipocalin-2 and the pathogenetic mechanisms of psoriasis/PsA." (PMID 31467617, 2019). "Serum LCN2 concentration is associated with the degree of itch in patients with psoriasis, suggesting that serum LCN2 may be a useful clinical marker for itch in psoriasis." (PMID 30805373, 2019). "In addition, by confirming that AOA significantly reduced the expression of psoriasis-associated antimicrobial peptides (Defb4, Lcn2, S100a7, and S100a9), we revealed that AOA ameliorated psoriasis-related symptoms and had anti-inflammatory effects in a mouse model of psoriasis." (PMID 37649889, 2023).
psoriasis (continued). "Among others, important psoriasis-associated target genes of IκBζ include certain chemo- and cytokines (e.g., Cxcl1, Cxcl2, Cxcl5, Ccl3, and Il17c) as well as antimicrobial proteins, such as S100 calcium-binding proteins (e.g., S100a9), β-defensin-2 (Defb4), and lipocalin-2 (Lcn2)." (PMID 31622280, 2019). "Serum lipocalin-2 levels might be a potential risk factor or biomarker for psoriasis/PsA." (PMID 31467617, 2019). "Elevated levels of LCN2 have been found in psoriasis, suggesting its potential involvement in the pathogenesis of psoriasis." (PMID 40369189, 2025). "We observed that, compared to normal controls, TWEAK was highly expressed in macrophages, LCN2 was highly expressed in neutrophils, and both TWEAK and LCN2 were highly expressed in keratinocytes within the lesional skin of psoriasis patients." (PMID 40369189, 2025). "To further investigate the effects of LCN2 on psoriasis, we utilized Lcn2–/– mice and subjected them to IMQ treatment for 6 days." (PMID 40369189, 2025). "We then investigated the underlying pathogenic mechanisms of LCN2, TWEAK, and Fn14 involved in psoriasis." (PMID 40369189, 2025). "Psoriasis is a chronic immune-mediated inflammatory cutaneous disease characterized by elevated levels of inflammatory cytokines and adipokine Lipocalin-2 (LCN-2)." (PMID 39057409, 2024). "Our results showed a reduction in neutrophils, macrophages, and T cells in inflamed skin, recapitulating a study in psoriasis showing LCN2-dependent skin infiltration." (PMID 39399497, 2024). "The authors have shown that the levels of lipocalin-2 are higher in those with acute forms of psoriasis, such as erythrodermic and pustular psoriasis, compared to those with chronic forms." (PMID 38399624, 2024). "LCN-2 has recently been proposed as a potential target for psoriasis treatment, since it is involved in keratinocyte differentiation and pathogenesis of psoriasis by stimulating neutrophil function, Th17 activation, and secretion of IL-23 by dendritic cells." (PMID 39057409, 2024). "In the last few years, several studies have also revealed that adipokine Lipocalin-2 (LCN-2) is highly expressed in psoriatic patients and in psoriasis mouse models." (PMID 39057409, 2024). "Defb4 and Lcn2 are psoriasis-specific antimicrobial peptides highly expressed in psoriatic plaques, and Defb4 can attract Th17 cells." (PMID 37649889, 2023). "Consistent with our findings, the neutralization of LCN2 has been shown to control neutrophilic inflammation in experimental disease models of psoriasis, cardiovascular disease, alcoholic steatohepatitis, and nonalcoholic steatohepatitis." (PMID 37371057, 2023). "To examine the anti-inflammatory effect of AOA on psoriasis, we observed changes in the expression of antimicrobial peptides, such as defensin β 4 (Defb4), lipocalin 2 (Lcn2), S100a7, and S100a9, which are known to amplify local inflammatory processes." (PMID 37649889, 2023). "Detected in blood samples through ELISA, lipocalin-2 is an adipokine that has been correlated with disease severity in psoriasis patients." (PMID 37546687, 2023). "We further used Western blotting and RT-PCR to confirm that BZLF downregulated the expression of LCN2 in IMQ-induced psoriasis-like mouse skin lesions." (PMID 36950008, 2023). "In dermatitis, serum Lcn2 levels in patients with psoriasis were significantly higher than those in healthy controls; in patients with psoriasis, serum Lcn2 concentrations significantly correlated with the visual analog scale (VAS)." (PMID 36983014, 2023). "LCN2 is highly expressed in the skin lesions and the serum of patients with psoriasis and can inhibit the synthesis of keratin, involucrin, and loricrin in KCs, leading to epidermal parakeratosis via the Tcf7L1-lipocalin 2 signaling axis." (PMID 36950008, 2023).
psoriasis (continued). "Although we confirmed that externally applied BZLF ameliorates psoriasis-like lesions by inhibiting LCN2, we found that its downstream genes Serbp2 and Nlrc4 were not in our DEG list, as determined by RNA-seq." (PMID 36950008, 2023). "The proinflammatory activity of NETs and LCN2 induction in psoriasis was suggested to be dependent on TLR4/IL-36R crosstalk and MyD88/nuclear factor-kappa B (NF-kB) downstream signaling." (PMID 37746070, 2023). "Among them, the expression of IL17A is predominant in psoriasis skin lesions, and IL-17 increases the secretion of antimicrobial peptides (Defb4, Lcn2, S100a7, and S100a9) by keratinocytes." (PMID 37649889, 2023). "Harder and Schröder reported that NGAL/Lcn2 expression is low in healthy skin but is increased in diseases such as psoriasis due to inflammatory conditions." (PMID 35935055, 2022). "Recent studies have demonstrated increased serum levels of lipocalin-2 in inflammatory disorders including psoriasis, atopic dermatitis or rheumatoid arthritis." (PMID 35639706, 2022). "LCN2 is increased in the blood and lesional skin of patients with psoriasis, and a correlation with LDL cholesterol levels was also demonstrated in these patients." (PMID 34639156, 2021). "After injection of LCN2 into imiquimod (IMQ)-induced psoriasis-like skin, the mRNA expression levels of IL17A, CXCL1, CCL20, S100A7, and other cytokines and chemokines increased, which supports our analysis results." (PMID 33613635, 2021). "LCN2 is critical for the inflammation in retinal degeneration, ocular disease, intestinal tract, ischemic stroke, psoriasis, cardiovascular diseases, alcoholic steatohepatitis, nonalcoholic steatohepatitis (NASH), muscle-skeletal disorders, and lung infection." (PMID 34257811, 2021). "Another molecule which is suspected to play an important role in the pathogenesis of pruritus in psoriasis is lipocalin-2 (LCN2)." (PMID 33467067, 2021). "It is currently believed that IL17A is the core driving factor of the pathogenesis of psoriasis, and LCN2 plays an indispensable role in this disease by acting as an antibacterial peptide and as a trigger for neutrophil activation in psoriasis." (PMID 33613635, 2021). "We recently demonstrated that serum levels of LCN2 were elevated in patients with psoriasis, and that this increase correlated with the severity of pruritus." (PMID 33182442, 2020). "As concerns humans, lcn2 serum levels are increased in patients with Behçet’s disease and psoriasis compared to controls." (PMID 32183784, 2020). "LCN2 is a prominently expressed gene in psoriasis, and is one of the genes most prominently induced by NETs in keratinocytes." (PMID 31024570, 2019). "Serum LCN2 concentration has been reported higher in patients with psoriasis, but lower in patients with AD, than that in healthy controls." (PMID 30805373, 2019). "But the LCN2 levels together with psoriasis area and severity index (PASI) score significantly dropped after NBUVB treatment." (PMID 31649677, 2019). "We examined the change in serum LCN2 levels with psoriasis patients between before and after biologic treatment." (PMID 30805373, 2019). "In conclusion, the present study showed a close relationship between the degree of itch and serum LCN2 level in patients with psoriasis." (PMID 30805373, 2019). "In conclusion, the present study indicates that serum lipocalin-2 concentrations are higher in psoriasis/PsA patients than controls." (PMID 31467617, 2019). "Serum LCN2 concentration has been reported elevated in patients with psoriasis, but lower in patients with atopic dermatitis (AD)." (PMID 30805373, 2019). "This study examined the correlation between serum LCN2 levels and the degrees of itch in patients with psoriasis." (PMID 30805373, 2019). "In addition to its central effect, LCN2 may have peripheral effects, inducing neutrophil infiltration, migration, and activation, all of which have been associated with the pathologic development of psoriasis." (PMID 30805373, 2019).
psoriasis (continued). "Second, our meta-analysis emphasizes the mechanism between lipocalin-2 and psoriasis/psoriatic arthritis." (PMID 31467617, 2019). "The LCN2 expression in MCs not only shows a wider involvement of hMCs in infections but also opens a new avenue of research for MCs role in psoriasis and wound healing, where LCN2 is highly expressed." (PMID 31091692, 2019). "LCN2 is suggested to be involved in the pathogenesis of psoriasis/PsA by modulating neutrophil function and enhancing T-helper 17 response." (PMID 31467617, 2019). "Serum LCN2 concentrations were significantly higher in patients with psoriasis and AD than those in healthy controls." (PMID 30805373, 2019). "Serum LCN2 concentrations in patients with psoriasis were significantly correlated with VAS scores (r = 0.4857P < 0.0001), but not with PASI." (PMID 30805373, 2019). "Serum LCN2 levels in psoriasis patients significantly decreased after the biological treatment along with improvement of VAS." (PMID 30805373, 2019). "Our meta-analysis indicated that serum lipocalin-2 levels were significantly higher in psoriasis/PsA patients than in controls (SMD: 0.757, 95%CI = 0.588‐0.926, and PH = 0.114; PH is the P value for the heterogeneity test)." (PMID 31467617, 2019). "Serum LCN2 concentration was shown to be higher in psoriatic patients and LCN2 was found to contribute to the pathogenesis of psoriasis by modulating neutrophil function to enhance T-helper 17-type responses." (PMID 30805373, 2019). "In our previous work, we have demonstrated that LCN2 potentiates inflammation by acting as a chemoattractant and as a trigger for neutrophil activation in psoriasis." (PMID 31024570, 2019). "The present study demonstrated that serum LCN2 levels were higher in patients with psoriasis and AD than those in healthy controls and that only the degree of itch in psoriasis correlated with serum LCN2 levels." (PMID 30805373, 2019). "In patients with psoriasis, serum LCN2 concentrations were significantly correlated with VAS, but not with PASI." (PMID 30805373, 2019). "Subsequently, we evaluated the association between serum levels of adipokines (adiponectin, omentin, chemerin, visfatin, lipocalin-2, and resistin) and psoriasis." (PMID 29416693, 2018). "The pooled serum levels of TNF-α, IFN-γ, IL-2, IL-6, IL-8, IL-18, IL-22, chemerin, lipocalin-2, resistin, sE-selectin, fibrinogen and C3 were higher in psoriasis patients compared with healthy controls (all P < 0.05)." (PMID 29416693, 2018). "We found that serum levels of three proinflamatory adipokines (chemerin, lipocalin-2 and resistin) were increased, while serum levels of one anti-inflammatory adipokine, adiponectin, were decreased in psoriasis patients." (PMID 29416693, 2018). "Serum levels of TNF-α, IFN-γ, IL-2, IL-6, IL-8, IL-18, IL-22, chemerin, lipocalin-2, resistin, sE-selectin, fibrinogen, complement 3, and adiponectin correlate with psoriasis and can be used as potential biomarkers for psoriasis and response to the treatment." (PMID 29416693, 2018). "Lipocalin-2 is expressed in neutrophils, monocytes, and keratinocytes; its serum levels are increased in patients with psoriasis and correlates with disease severity." (PMID 26849645, 2016). "LCN2 expression is upregulated in various acute and chronic inflammatory diseases such as psoriasis, eczema, periodontitis, and myocarditis." (PMID 24803721, 2014). "Namely, RHCG, TCN1, KLK6, and LCN2 were chosen for psoriasis and CCL17, NCF4, BATF3, and CLEC4G as ACD-specific genes." (PMID 25058585, 2014). "In this study, we found that serum LCN2 levels were significantly increased in patients with psoriasis compared with healty controls." (PMID 24803721, 2014). "LCN2 is highly expressed in the lesions and serum of patients with psoriasis." (PMID 40369189, 2025).
psoriasis (continued). "Consequently, the deletion of Lcn2 appears to modulate leukocyte migration and have a regulatory effect on the release of inflammatory cytokines, leading to the alleviation of psoriasis-like skin lesions." (PMID 40369189, 2025). "We propose that LCN2 synergizes with TWEAK through Fn14 to drive psoriasis pathogenesis." (PMID 40369189, 2025). "To further validate that LCN2 promotes psoriasis development by interacting with Fn14, we stimulated Fn14-overexpressing keratinocytes with rhLCN2 and observed that these keratinocytes were more readily activated and exhibited higher expression levels of inflammatory factors." (PMID 40369189, 2025). "Furthermore, the transcriptional signature from affected skin revealed upregulation of key human psoriasis genes, including Lcn2 and Defb4, cytokines Tnf, Il1b, and Il36a/g, and chemokine ligands Ccl2, Cxcl9, and Ccl20." (PMID 38528069, 2024). "In psoriasis, LCN2 modulated neutrophil activation and mediated skin inflammation." (PMID 39480805, 2024). "Finally, in our psoriasis mouse model, we have revealed that plasma levels of LCN-2 were lowered during oral administration of POE." (PMID 39057409, 2024). "Interestingly, a few studies have shown that increased LCN-2 levels have an important role in psoriasis and that LCN-2 is secreted by neutrophils and keratinocytes." (PMID 37631238, 2023). "Therefore, MMP-9 was chosen to examine the possible mechanism by which BZLF downregulates LCN2 to improve psoriasis-like skin lesions." (PMID 36950008, 2023). "To further examine the regulatory mechanism by which BZLF acts on LCN2 to improve psoriasis-like skin lesions, we used the STRING database to predict target genes that might interact with LCN2 based on the DEGs from the RNA-seq results." (PMID 36950008, 2023). "Furthermore, lipocalin-2 levels were significantly higher in patients with acute types of psoriasis than in chronic types, indicating the potential of this adipokine as a biomarker for psoriasis accompanied with acute inflammation." (PMID 37546687, 2023). "Lipocalin-2 (LCN2) is significantly higher in patients with psoriasis than in healthy controls, and may be used as a clinical indicator of psoriatic pruritus." (PMID 34134787, 2021). "Additionally, LCN2 was found to contribute to the pathogenesis of psoriasis by modulating neutrophil function to enhance T-helper 17-type responses." (PMID 33467067, 2021). "Based on these findings, LCN2 may also be partially involved in the aggravation of pruritus in psoriasis." (PMID 33182442, 2020). "The similar results of studies with irisin and LCN-2 in HS and psoriasis patients may indicate a possible pathogenetic link between these two conditions." (PMID 33008659, 2020). "However, it is still necessary to conduct more large-scale studies to further explore the pathogenetic mechanisms of LCN2 in psoriasis/PsA." (PMID 31467617, 2019). "Serum lipocalin-2 concentrations are higher in psoriasis/PsA patients than controls." (PMID 31467617, 2019). "LCN2 may contribute to the pathogenesis of psoriasis by modulating neutrophil activities, including neutrophil infiltration, migration, and activation, inducing neutrophils to release proinflammatory mediators." (PMID 30805373, 2019). "We also compared serum LCN2 levels before and after biologic treatment with 14 psoriasis patients." (PMID 30805373, 2019). "Notably, both TLR4 inhibition and LCN2 neutralization alleviate psoriasis-like inflammation and NETs formation in both the IMQ model and K14-VEGF transgenic mice." (PMID 31024570, 2019). "Moreover, some studies have reported that serum LCN2 levels are increased in psoriasis patients than controls." (PMID 31467617, 2019). "LCN2, the most highly expressed inflammatory mediator in NETs-treated keratinocytes, has been reported previously by our group to be abundant in the skin lesions of psoriasis patients and modulate neutrophil functions." (PMID 31024570, 2019).